BEX2 (brain expressed X-linked 2)
Description:
Regulator of mitochondrial apoptosis and G1 cell cycle in breast cancer. Protects the breast cancer cells against mitochondrial apoptosis and this effect is mediated through the modulation of BCL2 protein family, which involves the positive regulation of anti-apoptotic member BCL2 and the negative regulation of pro-apoptotic members BAD, BAK1 and PUMA. Required for the normal cell cycle progression during G1 in breast cancer cells through the regulation of CCND1 and CDKN1A. Regulates the level of PP2A regulatory subunit B and PP2A phosphatase activity. In absence of reductive stress, acts as a pseudosubstrate for the CRL2(FEM1B) complex: associates with FEM1B via zinc, thereby preventing association between FEM1B and its substrates (By similarity).
Synonyms: DJ79P11.1; BEX1
Tractability: PROTAC: ubiquitination databases record sites on it.
Gene: Protein-coding gene on chromosome X (103,309,345 to 103,311,298, reverse strand). Ensembl gene ENSG00000133134.
Subcellular location: Cytoplasm; Nucleus
Subcellular location (Human Protein Atlas): Cytosol
Gene Ontology:
Molecular function: protein binding; molecular function inhibitor activity; signaling receptor binding
Biological process: regulation of apoptotic process; regulation of cell cycle; negative regulation of protein ubiquitination; signal transduction
Cellular component: nucleus; cytoplasm
Homologues: Orthologues: chimpanzee BEX2 (98% identical), macaque BEX2 (98% identical), pig BEX1 (81% identical), rat Bex2 (74% identical), mouse Bex2 (72% identical), mouse Bex1 (67% identical), rat LOC100912195 (64% identical). Paralogues in human: BEX1 (89% identical), BEX5 (37% identical), BEX3 (31% identical).
Diseases named in the same sentence as BEX2 in open-access papers:
BEX2 is named in the same sentence as 48 diseases in open-access papers, as found by Europe PMC text mining. Sharing a sentence is not in itself a finding about the gene and the disease. The quoted sentences say what the papers report.
breast carcinoma (16 papers, 2010 to 2024). "A protein encoded by BEX2 was demonstrated to exert anti-apoptotic effects when overexpressed in breast cancer cells and malignant glioma cells." (PMID 37373173, 2023). "Brain expressed X-linked 2 (BEX2) has been shown to control mitochondrial apoptosis and the G1 cell cycle in breast cancer and to increase the proliferation of human glioblastoma cells." (PMID 35865542, 2022). "BEX2 activates the NF-kB pathway and thus inhibits ceramide 2 (C2) apoptosis of breast cancer cells." (PMID 34803456, 2021). "BEX2 has been shown that it activates the NF-kB signaling pathway in breast cancer cells, promotes the human glioblastoma cells proliferation via the NF-κB signaling pathway." (PMID 34803456, 2021). "c-Jun and p65/RelA transcription factors targeting BEX2 are being phosphorylated in breast cancer cells." (PMID 34803456, 2021). "BEX2 is overexpressed in a subset of primary breast cancers and mediates the inhibition of apoptosis of breast cancer cell lines through nerve growth factor/nuclear factor kappa-light-chain-enhancer of activated B cells (NF-κB)." (PMID 29784063, 2018). "BEX2 has also been shown to be required for progression of MCF-7 breast cancer cells through the G1 phase of the cell cycle via its regulation of cyclin D1 and p21." (PMID 24212627, 2011). "In breast cancer cells, a novel adaptor Bex2 has recently been shown to be required for NGF/p75NTR-dependent NF-κB activation and prosurvival effects." (PMID 24212627, 2011). "BEX2 is overexpressed in a subset of primary breast cancers and mediates nerve growth factor/nuclear factor-kappaB inhibition of apoptosis in breast cancer cell lines." (PMID 21627793, 2011). "In this study we investigated the transcriptional regulation of BEX2 and feedback mechanisms mediating the cellular function of this gene in breast cancer." (PMID 20482821, 2010). "Our findings suggest that BEX2 is involved in a novel feedback mechanism with significant implications for the biology of breast cancer." (PMID 20482821, 2010). "The functional data presented in this study suggest that BEX2 has a regulatory feedback loop with c-Jun and p65 signaling in breast cancer cells." (PMID 20482821, 2010). "Overall, these results demonstrate that BEX2 is a target gene for c-Jun and p65/RelA in breast cancer." (PMID 20482821, 2010). "We have previously demonstrated that BEX2 is differentially expressed in breast tumors and has a significant role in promoting cell survival and growth in breast cancer cells." (PMID 20482821, 2010). "BEX2 expression protects breast cancer cells against mitochondrial apoptosis and G1 cell cycle arrest." (PMID 20482821, 2010). "In this respect, BEX2 expression protects breast cancer cells against mitochondrial apoptosis and is necessary for the normal transition of these cells through G1 cell cycle." (PMID 20482821, 2010). "Although BEX2 shows a relatively higher expression in 15% of breast cancers, this gene is expressed in the majority of breast tumors and breast cancer cell lines." (PMID 20482821, 2010). "To further study our findings using actual breast cancer tissue, we investigated a correlation between the expression of BEX2 and c-Jun in primary breast tumors." (PMID 20482821, 2010). "BEX2 down-regulation induces mitochondrial apoptosis and sensitizes breast cancer cells to pro-apoptotic agents and conversely, BEX2 overexpression protects these cells against mitochondrial apoptosis." (PMID 20482821, 2010). "In order to investigate the transcriptional regulation of BEX2, we first examined the factors involved in the regulation of BEX2 expression in breast cancer cells." (PMID 20482821, 2010). "All together, these findings suggest that BEX2 expression is required for c-Jun-mediated induction of cyclin D1 and cell proliferation in breast cancer cells." (PMID 20482821, 2010). "These suggest that BEX2 is involved in a novel feedback mechanism with significant implications for the biology of breast cancer." (PMID 20482821, 2010).
breast carcinoma (continued). "Overall these data demonstrate that BEX2 is a target gene for c-Jun and p65/RelA in breast cancer cells." (PMID 20482821, 2010). "Taken together, these findings suggest that BEX2 expression is required for both normal phosphorylation of p65 and IκBα, and the ceramide induced DNA binding of p65 in breast cancer cells." (PMID 20482821, 2010). "We have previously demonstrated that BEX2 has a significant role in promoting cell survival and growth in breast cancer cells." (PMID 20482821, 2010). "We have previously shown that BEX2 down-regulation results in a higher PP2A activity in breast cancer cells." (PMID 20482821, 2010). "In summary, this study shows that BEX2 has a functional interplay with c-Jun and p65/RelA in breast cancer." (PMID 20482821, 2010). "Notably, the authors also found that, in response to estradiol and tamoxifen, BEX2 modulates the apoptosis of breast cancer cells." (PMID 36354700, 2022). "BEX2 is a regulator of mitochondrial apoptosis and G1 cell cycle in breast cancer." (PMID 35175539, 2022). "Bex2 regulates mitochondrial apoptosis and the G1 cell cycle in breast cancer." (PMID 32676117, 2020). "BEX2 promotes the growth of breast cancer cells partly through up-regulation of NF-κB signaling." (PMID 29029472, 2017). "BEX2 is overexpressed in breast cancer and facilitates the growth of breast cancer cells." (PMID 29029472, 2017). "Bex2 has a significant role in promoting cell survival and growth in breast cancer cells, and Rassf2 might function as a tumor suppressor gene in in vitro cell migration and cell cycle progression." (PMID 23555558, 2013). "Next we demonstrated that BEX2 has a feedback mechanism with c-Jun and p65/RelA in breast cancer." (PMID 20482821, 2010). "Therefore, understanding the transcriptional regulation of BEX2 is a critical step to advance our knowledge about the function of this gene in the biology of breast cancer." (PMID 20482821, 2010). "Furthermore, our data suggest that BEX2 expression is required for the normal cell cycle progression during G1 in breast cancer cells through the regulation of cyclin D1." (PMID 20482821, 2010). "However, we have not found any correlation between BEX2 expression and promoter methylation in breast tumors or any evidence for gene amplification to explain the differential expression of BEX2 in breast cancer." (PMID 20482821, 2010). "Moreover, we have demonstrated that BEX2 has a significant role in promoting cell survival and growth in breast cancer cells." (PMID 20482821, 2010). "To gain a deeper understanding of the effects of BEX2 expression in c-Jun-mediated cellular functions we investigated the effect of BEX2 on cyclin D1 which is a known c-Jun target of obvious importance in breast cancer." (PMID 20482821, 2010). "Moreover, we have previously reported that BEX2 down-regulation in breast cancer cells leads to a G1 arrest and a significant reduction of cyclin D1 expression." (PMID 20482821, 2010). "These suggest that disturbances in transcriptional regulation may be a mechanism for the observed pattern of BEX2 expression in breast cancer." (PMID 20482821, 2010). "In addition to our data in breast cancer, BEX2 is found to be differentially expressed in acute myeloid leukemia with a higher expression observed in MLL subtype." (PMID 20482821, 2010). "This study shows that BEX2 has a functional interplay with c-Jun and p65/RelA in breast cancer." (PMID 20482821, 2010). "In breast cancer, BEX2 could modulate ceramide-induced apoptosis via protein phosphatase 2A." (PMID 27297407, 2016). "BEX2 in turn regulates the phosphorylation of c-Jun, p65, and IκBα as well as JNK kinase activity in breast cancer cells." (PMID 20482821, 2010). "This study suggests that BEX2 has a functional interplay with c-Jun/JNK and p65, which has significant implications for the biology of breast cancer." (PMID 20482821, 2010). "In breast cancer, overexpression of BEX1 and BEX2 can inhibit the apoptosis of tumor cells." (PMID 37745297, 2023).
breast carcinoma (continued). "Furthermore, we have recently shown that BEX2 regulates PP2A expression and activity in breast cancer cells." (PMID 20482821, 2010). "Furthermore, we show that BEX2 is necessary for the phosphorylation of c-Jun/JNK and p65 in breast cancer cells." (PMID 20482821, 2010). "Furthermore, BEX2 overexpression enhances the antiproliferative effect of tamoxifen, suggesting the involvement of the NGF/BEX2/NF-kB pathway in the modulation of the response to the hormonal drug in primary breast cancer." (PMID 36354700, 2022). "Although it has not been shown whether or not BEX2 interacts directly with p75NTR, it is reported to be necessary and sufficient for the anti-apoptotic function of NGF in breast cancer cells." (PMID 24212627, 2011).
glioma (12 papers, 2010 to 2025). A benign or malignant brain and spinal cord tumor that arises from glial cells (astrocytes, oligodendrocytes, ependymal cells). "Recent reports have implicated that BEX2 is involved in tumor development and progression in several types of cancer, such as glioblastoma, glioma and breast cancer 7-9." (PMID 31929751, 2020). "Bex2 overexpression is associated with increased activation of the Bcl-2/NF-κB pathway in primary breast tumors and glioma cells." (PMID 25612294, 2015). "A genome-wide association study (GWAS) revealed that Bex2 might act as a tumor inhibitor in glioma’s virulence." (PMID 34803456, 2021). "On the contrary, in primary glioma, BEX2 is epigenetically silenced and exhibits extensive promoter hypermethylation, and re-expression of BEX2 results in significantly suppressed tumor proliferation." (PMID 31929751, 2020). "This decrease in BEX2 expression impairs vasculogenic mimicry channel formation in vitro and angiogenesis in vivo, and modulates glioma cell adhesion, motility and invasive features." (PMID 19371355, 2010). "Furthermore, PLXND1 has been found to be a transcriptional target of the NOTCH signaling pathway, and BEX2 has been suggested as a tumor suppressor gene in glioma." (PMID 40788820, 2025). "However, some studies show contrasting results about BEX2, such as its high expression in glioma tissue and its role in inhibiting glioma cell migration and invasion by affecting β-catenin levels." (PMID 39874307, 2025). "In U251 astrocytoma and U87 glioma cell lines, BEX2 is essential for migration and invasion." (PMID 33299012, 2020). "It is also reported that BEX2 expression is upregulated in glioma tissues." (PMID 29029472, 2017). "BEX2, part of the BEX gene family, was found to be silenced in U-87 and primary glioma cell lines, with its re-expression increasing sensitivity to chemotherapy-induced apoptosis and demonstrating tumor suppressor effects." (PMID 39874307, 2025). "Besides, the expression of BEX2 protects glioma cells against apoptosis mediated via the JNK pathway and is essential for glioma cell proliferation through the NF-κB p65." (PMID 34803456, 2021). "In glioma, BEX1 and BEX2 are silenced and the expression could be activated by treatment with DNA methyltransferase inhibitor and histone deacetylase inhibitor." (PMID 27297407, 2016). "To confirm that BEX2 and CD274 are mutually exclusive in their expression, we tested BEX2 and CD274 protein expression by western blot or flow cytometry using 16 cell lines derived from various cancers, including cholangiocarcinoma, hepatocellular carcinoma, gastric cancer, lung cancer, and glioma." (PMID 33299012, 2020).
glioblastoma (7 papers, 2010 to 2025). The most malignant astrocytic tumor (WHO grade IV). "Recent papers implicated ORP150, a major pro-angiogenic gene and BEX2 (brain-expressed X-linked gene) in Gal-1 triggered pathways of in vivo and in vitro angiogenesis in glioblastoma tumors." (PMID 22844466, 2012). "In brain tumors, BEX2 enhances cell moment and invasion in oligodendroglioma and glioblastoma cells." (PMID 34803456, 2021). "Re-expression of Bex1 or Bex2 gene by transduction enhanced chemosensitization and apoptosis in glioblastoma cells." (PMID 28145533, 2017). "Bex1 and Bex2 have been identified as tumor suppressor genes and are silenced in malignant glioblastoma." (PMID 28145533, 2017). "In our study, TQ treatment of A172 glioblastoma cells with 25 and 50 μM concentrations for 48 hours significantly up-regulated two candidate tumor suppressor genes: Sprouty RTJ Signaling Antagonist 4 (SPRY4) and Brain Expressed X-Linked 2 (BEX2)." (PMID 39874307, 2025). "BEX2 plays a role in promoting human glioblastoma cells’ propagation via NF-kB signaling pathway." (PMID 34803456, 2021). "Furthermore, in MLL wild-type AML and glioblastoma BEX2 expression is regulated by epigenetic silencing such as promoter methylation." (PMID 20482821, 2010). "Furthermore, in AML and glioblastomas BEX2 expression is regulated by epigenetic mechanisms such as promoter methylation." (PMID 20482821, 2010).
acute myeloid leukemia (5 papers, 2009 to 2021). Acute myeloid leukemia (AML) is a group of neoplasms arising from precursor cells committed to the myeloid cell-line differentiation. "BEX2 is differentially expressed in breast tumors, acute myeloid leukemia, and an increased expression was found in the MLL subtype." (PMID 34803456, 2021). "For acute myeloid leukemia (AML) cell lines, a similar correlation exists between MLL translocations and expression of the gene brain expressed X-linked 2 (BEX2, formerly called BEX1)." (PMID 19835597, 2009). "Additionally, BEX2 expression was increased in MLL mutant acute myeloid leukemia (AML) cells." (PMID 29029472, 2017).
breast tumors (5 papers, 2010 to 2024). "We have previously demonstrated that BEX2, a member of Brain Expressed X-linked gene family, is differentially expressed in breast tumors and BEX2 expression predicts the response to tamoxifen therapy." (PMID 20482821, 2010). "Moreover, BEX2 is differentially expressed in breast tumors and is associated with a characteristic gene-expression signature in this disease." (PMID 20482821, 2010). "The gene BEX2 has been recognized as being expressed at higher levels in a specific group of breast tumors that have estrogen receptors (ER)." (PMID 38970097, 2024). "We next examined a correlation between BEX2 and c-Jun protein levels in breast tumors using immunohistochemistry (IHC)." (PMID 20482821, 2010). "Overall, these findings demonstrate that BEX2 expression has a positive correlation with the expression of c-Jun and activation of p65 (nuclear) in primary breast tumors." (PMID 20482821, 2010). "We first assessed a possible correlation between the transcript levels of BEX2 and c-Jun in a cohort of 35 frozen breast tumors." (PMID 20482821, 2010). "For this purpose we first optimized the rabbit polyclonal BEX2 antibody for IHC application on frozen breast tumors." (PMID 20482821, 2010). "Taken together, these data indicate that there is a positive correlation between the expression of BEX2 and c-Jun in primary breast tumors." (PMID 20482821, 2010). "Subsequently, we studied the correlation between BEX2 and c-Jun protein levels in these breast tumors using IHC." (PMID 20482821, 2010). "It has been reported that BEX2 is differentially expressed in breast tumors." (PMID 34803456, 2021). "Furthermore, our findings suggest that the relative overexpression of BEX2 in a subset of breast tumors can be explained by a higher expression/activation of c-Jun and p65 transcription factors in this subset." (PMID 20482821, 2010). "We have also demonstrated that the transcriptional regulation of BEX2 by c-Jun and p65/RelA translated through to BEX2 protein expression and we were able to show that there is a strong correlation between BEX2 and c-Jun expression levels in primary breast tumors." (PMID 20482821, 2010). "Moreover, we have previously demonstrated that p65-nuclear staining by IF is approximately 2-fold higher in primary breast tumor samples with a relative overexpression of BEX2." (PMID 20482821, 2010). "It is notable that in contrast to these cancer types, we have not found any correlation between BEX2 expression and promoter methylation in breast tumors." (PMID 20482821, 2010). "Importantly, as opposed to the down-regulation of BEX2 expression observed in gliobalstoma there is a relative overexpression of this gene in breast tumors, which suggests a difference in the transcriptional regulation of BEX2 between these cancers." (PMID 20482821, 2010).
colorectal cancer (5 papers, 2020 to 2025). A primary or metastatic malignant neoplasm that affects the colon or rectum. "The similar pathway of BEX2-JNK has also been reported in colorectal cancer to promote the tumor proliferation." (PMID 39021802, 2024). "In summary, our findings suggest that BEX2 negatively modulates the hedgehog signaling pathway by retaining Zic2 in the cytoplasm in colorectal cancer cells, thereby inhibiting migration and metastasis of colorectal cancer cells." (PMID 31929751, 2020). "Herein, we demonstrated that BEX2 knockout resulted in enhanced migratory and metastatic potential in colorectal cancer cells both in vitro and in vivo, and re-expression of BEX2 in knockout cells could reverse the enhanced migratory capacity." (PMID 31929751, 2020). "RNA-Seq results indicated that the hedgehog signaling pathway was activated after BEX2 knockout; moreover, the hedgehog signaling inhibitors, GANT61 and GDC-0449 could reverse the migratory enhancement of BEX2-/- colorectal cancer cells." (PMID 31929751, 2020). "In contrast, brain-expressed X-linked 2 (BEX2) protein displayed a negative modulation of SHH signaling by retaining ZIC2 in the cytoplasm and inhibiting its nuclear translocation in colorectal cancer cells, hence inhibiting their migration and metastasis." (PMID 40952541, 2025).